IL2 (interleukin 2)
Diseases named in the same sentence as IL2 in open-access papers (continued):
Sharing a sentence is not in itself a finding about the gene and the disease.
cancer (continued). "The results show that the mfhAXL CAR-T cells specifically secreted elevated levels of interleukin-2 (IL-2) and interferon-γ (IFN-γ) when co-cultured with A549 and Panc-1 cancer cells, as compared to control T cells, which indicate specific T-cell activation in the presence of target cells." (PMID 40299452, 2025). "Two anti-cancer cytokines MICA and IL-2 are consistently increased with combinational treatment." (PMID 40145650, 2025). "Recent articles focus mainly on the role of IL-2 in immune response and cancer rather than its relationship with aging." (PMID 41305439, 2025). "According to the results of GSEA in pan-cancer, NCBP2 was closely related to immune related pathways, such as IFN-alpha response, IFN-gamma response, IL-6/JAK/STAT3 signaling, IL-2/STAT5 signaling, allograft-rejection pathways, inflammatory response, and TNF alpha signaling-via NFKB." (PMID 40124611, 2025). "CD8+T-cells are key in cancer defense, maturing into cytotoxic cells through TCR engagement with MHC-II on APCs, supported by co-stimulatory signals (CD28/CD80/CD86) and cytokines like IL-2, IFN-γ, and IL-9 from Th1 and Th9 cells." (PMID 40260236, 2025). "In the 1970s, interleukin-2 (IL-2) and interferons were employed in cancer treatment, driving the development of non-specific immunotherapy." (PMID 40264788, 2025). "Nowadays, recombinant IL-2, IFN-α and TNF are applied into cancer immunotherapy." (PMID 41333471, 2025). "As of 2023, no IL-2-enhanced compounds had been approved for the treatment of cancer patients, with the exception of NKTR-214." (PMID 39852848, 2025). "These modifications involve expressing immunostimulatory heterologous genes, such as interleukin-12 (IL-12), granulocyte/macrophage colony-stimulating factor (GM-CSF), interferon-gamma (IFN-γ), interleukin-2 (IL-2), or tumor necrosis factor-alpha (TNF-α) in various human cancers." (PMID 40722781, 2025). "Since the different pathways activated by the binding of IL-2 to its receptor expressed on the surface of the cancer cells are not yet known, to clarify these observations, a new project should be started." (PMID 41150778, 2025). "IL‐2, as reported, can boost CD4+ T cells to secrete Gzms‐B to eliminate cancer cells." (PMID 38953306, 2024). "The correlation analysis of LY6H expression and immunomodulatory genes revealed a significant association between LY6H expression and immunomodulatory genes across various cancer types, including pivotal immune genes such as IL2RA (also known as CD25), IL-2, and CTLA423." (PMID 39308669, 2024). "Therefore, the aim of this study was to compare levels of IL-2 and the p40 subunit of IL-12 and IL-23 (IL-12/IL-23p40) in blood from healthy NSDTRs and NSDTRS with a diagnosis of IMRD, SRMA or cancer." (PMID 38773194, 2024). "Consequently, inflammatory molecules such as the interleukin 2 (IL‐2) and tumor necrosis factor alpha (TNF‐⍺) are released, simulating cancer death through necrosis or apoptosis." (PMID 38894611, 2024). "IL-2/S4B6 immune complexes exhibit high stimulatory activity toward NK cells and CD8 T cells; they could potentially replace conventional IL-2 in cancer immunotherapy." (PMID 39317690, 2024). "Among them, interleukin 2 (IL-2), interferon (IFN), and granulocyte-macrophage colony-stimulating factor (GM-CSF) are the classical therapeutic cytokines used in cancer therapy." (PMID 39334825, 2024). "The synergy between IL-2's immune amplification and IPCGOR's direct cytotoxicity results in a robust and comprehensive anti-cancer action.In terms of adverse events, our study observed a spectrum of reactions consistent with both chemotherapy and immunotherapy." (PMID 38434976, 2024). "Initially, bisphosphonate-based drugs, such as PAM, ZOL, and IL-2, were found to stimulate Vγ9Vδ2 T cells but were not clinically effective in cancer models." (PMID 38397462, 2024).
cancer (continued). "Human-derived cytokines interleukin-2 (IL-2), IL-4, IL-6, IL-12, IL-10, tumor necrosis factor α (TNF-α), and interferon-γ (IFN-γ) could be detected in all cancer cell–bearing mice by cytokine level measurement." (PMID 39606226, 2024). "Also, there is evidence to suggest that, in the presence of CeNPs, T-cells can release more interleukin-2 (IL-2) and tumor necrosis factor-α (TNF-α), helping to provide more effective cancer therapy." (PMID 37896153, 2023). "Therefore, the PD-L1 targeting of IL-15 differentiates KD033 treatment from ICIs, free IL-15, modified free IL-2, or immune-checkpoint inhibitor treatments, and highlights the merit of KD033’s testing in various cancer indications." (PMID 36454338, 2023). "Lumican-IL-2 and lumican-IL-12 also enhanced combined therapies such as therapeutic antibodies, cancer vaccines and CAR-T therapy without systemic toxicity." (PMID 37692860, 2023). "Hence, like IL-2/S4B6 complexes, IL-2 muteins with poor binding to Tregs can be used to selectively stimulate CD8 cells and NK cells, thereby being useful for cancer immunotherapy." (PMID 36675265, 2023). "The anti-cancer effects of IL-2-activated lymphocytes is not new but originally considered clinically relevant for activating patient’s own anti-cancer effector cells in patients with cancer." (PMID 37202579, 2023). "Our previous reports found out TCPT activated inflammation in H22 tumor bearing mice through producing IL-2 and TNF-α, which imply TCPT might be a pro-inflammatory factor in cancer treatment." (PMID 36597133, 2023). "It reduced toxicity without losing the ability of IL-2 to activate the immune system to fight cancer." (PMID 37046608, 2023). "A combination of high-dose Ipilimumab along with high-dose interleukin-2 (IL-2) has shown an enhanced response rate, survival without cancer progression, or a larger percentage of complete responses of all desirable outcomes." (PMID 37803407, 2023). "In addition, when cancer cells were co-cultured with Jurkat T cells, MTSS1 knockdown in H1975 significantly decreased IL-2 secretion from T cells." (PMID 36810288, 2023). "In particular, lenalidomide was also reported to promote the secretion of interleukin-2 (IL-2) and IFN-γ from T cells, which may allow its dual role in suppressing cancer proliferation and activating T-cell function." (PMID 37631380, 2023). "Importantly, Tregs constitute a key CD3+CD4+ subset that inhibits an effective anti-cancer immune response by producing the immunosuppressive cytokines IL-10 and TGF-β and consuming IL-2." (PMID 36980527, 2023). "During chronic infection and cancer, the TME highly exists various pro-inflammatory factors, which greatly contribute to setting free complex negative regulatory factors, for instance IL-10, TGF-β, and IL-2, thereby making T cell exhaustion appeared." (PMID 37106742, 2023). "IL-2 is a pleiotropic cytokine mainly produced by antigen-stimulated CD4+T lymphocytes, which has as an important role in promoting a cellular immune response against intracellular microorganisms and cancer cells." (PMID 36984496, 2023). "The results showed that RS was closely related to KRAS signaling up, EMT and other pathways related to cancer development and metastasis, and the immune-related pathways IL6 JAK STAT3 signaling and IL2 STAT5 signaling were significantly different in patients with high and low RS." (PMID 37773804, 2023). "IL-2, TNF-α, and NO were used as markers for cancer prevention." (PMID 37296375, 2023). "NK cells were purified from PBMC of healthy donors and added to re-seeded A549 cells at 10:1 (NK to cancer cells) ratio in the presence or absence of IL-2." (PMID 36656721, 2023). "In addition to its upregulation of antigen processing and presentation, JQ1 also promoted Interleukin‐2 (IL2) family signaling, interferon‐γ (IFNG) signaling, and cytokine signaling in cancer cells." (PMID 37271874, 2023).
cancer (continued). "It was discovered that taking probiotic supplements not only reduced the synthesis of inflammation-related proteins and pro-inflammatory cytokines like IL-1 and IL-2 but also increased the production of anti-inflammatory cytokines like IL-10 and TGF- during the course of cancer." (PMID 36263037, 2022). "The safety and efficacy of α-PD-1/PD-L1 combined with IL-2 pathway agonist (NKTR-214/BEMPEG), PEGylated IL-10 (Pegilodecakin), IL-12 plasmid (Tavo), IL-15 agonist (ALT-803), or PEGylated IFN-α had been validated in cancer patients." (PMID 35062949, 2022). "The coated leukocytes could be considered as “un-natural killer cells”, because they resemble natural killers activated by IL-2, which overexpresses TRAIL to attack and induce apoptosis in cancer cells." (PMID 36230630, 2022). "In this review, we discuss the various types of therapeutic cancer vaccines, including types of antigens and approaches used to enhance cancer vaccine responses such as TLR agonists, recombinant interleukin-2 and interleukin-2 derivatives, and checkpoint inhibitors." (PMID 35651800, 2022). "While in vitro ZOL treatment could reduce numbers of Treg cells and Treg suppression in cultured PBL from cancer patients, it remains unknown whether in vivo ZOL or ZOL/IL-2 administration can regulate Treg cells." (PMID 35765887, 2022). "Macrophages affect the cancer population indirectly by producing cytokines like IL6, IL10, and IL2." (PMID 35294447, 2022). "To overcome the lack of specificity of cancer therapeutics and thus create a more potent and effective treatment, we developed a novel chimeric protein, IL2-Smurf2." (PMID 36612252, 2022). "Here, IL-2 is a T cell growth factor, IFN and TNF areinflammatory cytokines, and CD107 is a component of the mechanism used by T cells todirectly kill infected and cancer cells." (PMID 36381997, 2022). "Pan-caner analysis indicated that NFE2L3 might promote the differentiation of Th2 cells through the IL-2/STAT5/NLRP3 signaling pathway in MPM and many other cancers." (PMID 35664314, 2022). "Our data demonstrated that IL-2 therapy suppressed GVHD and improved the overall survival without the evidence of cancer growth until week 6, suggesting that IL-2-expanded Treg under mild inflammatory conditions did not interfere with the GVL activity." (PMID 35983059, 2022). "IL-2, IL-4, and IL-12 may need to be modified or combined with other adjuvants, such as Montanide ISA-51 or GM-CSF in peptide-based cancer vaccine therapies to increase effectiveness." (PMID 35967400, 2022). "IL-2, which is recognized as a T cell growth factor to enhance memory T cell responses and regulate T cell maintenance, is the first FDA-approved immunotherapy for human cancer." (PMID 36014696, 2022). "A phase-IB/II trial (NCT03260023) of an HPV16 E6/E7 and IL-2 vaccine (TG4001) plus a PD-L1 inhibitor in patients with R/M HPV16-positive cancers that did not respond to available standard treatments demonstrated an ORR of 23.5%." (PMID 35887235, 2022). "The IL-2 diphtheria toxin conjugate Denileukin Diftitox (IL2DT), composed of the amino acid sequences for diphtheria toxin followed by truncated IL-2, is used to selectively deplete CD25-expressing Tregs and allow PB-NK cell expansion and in vivo function by the Masonic Cancer Center (row 1)." (PMID 36348457, 2022). "In the absence of monocytes, NK cells from cancer patients exhibited decreased cytotoxic function when treated with IL-2 alone, or IL-2+anti-CD16 mAbs, or IL-2 + sAJ2." (PMID 35203349, 2022).
cancer (continued). "Indeed, the use of OX40 agonists with ICIs, cytokines such as IL2 and IL12, chemotherapeutic drugs such as cyclophosphamide, or radiation therapy, has shown a synergic effect on different types of murine cancer." (PMID 34453261, 2021). "In cancer patients, besides IL-17, Th17 cells produce high levels of other immunological mediators, such as GM-CSF, IL-2, TNF and IFN-γ, but not IL-10." (PMID 34646761, 2021). "IL-15 demonstrated efficacy in murine models of cancer whilst studies in Macaques have demonstrated large increases in Tem CD8+ T-cell numbers, providing a rationale for its use as an alternative to IL-2." (PMID 34960140, 2021). "The development of an IL-2-based therapy that can preferentially expand CD8 T cells and NK cells limits adverse side effects and improves clinical efficacy will potentially be a powerful tool in the cancer treatment paradigm." (PMID 34790830, 2021). "Thus far, only two cytokines have been approved by the Food and Drug Administration for human cancer treatment: IFN-α and IL-2." (PMID 33922837, 2021). "Moreover, the expression of IL2, IL10, IL12, LAYN in pre-exhausted T cells were consistent with the expression of genes in other cancer, suggesting that pre-exhausted T cell have common features in immune microenvironment." (PMID 34434188, 2021). "IL-2 and IFN-α were the first cytokines approved for cancer therapy." (PMID 34579759, 2021). "As an example, IL-2 doses of 9–12 × 106 units daily may downregulate CYP activities in patients with HIV infection and cancer in whom this treatment is administered to boost the immune system." (PMID 34867341, 2021). "IL-2 increases the number and in vitro tumoricidal activity of NK cells and in vitro ADCC mediated by peripheral blood mononuclear cells obtained from patients with cancer can be enhanced dramatically if the patients were treated with IL-2." (PMID 33572900, 2021). "Low-dose supplementary IL-2 inhibits dexamethasone-induced apoptosis in CD8 T cells by activating STAT-5 and altering cellular apoptotic potential, and TAM suppression by dexamethasone improved the antitumor immune response in cancer xenograft mouse models." (PMID 34496935, 2021). "Our study suggested that cancer patients in T3-4 stages had lower levels of CD3+CD4+ T cells and CD19+ B cells, and patients in N2-3 stages had lower levels of CD19+ B cells and higher levels of IL-2." (PMID 34712741, 2021). "TIL-iPS-T were co-cultured with GFP-transduced cancer spheroids at a ratio of 1:1 in phenol red-free D-MEM supplemented with 10% fetal bovine serum, 2 mM l-glutamine, 100 U/ml penicillin, 100 ng/ml streptomycin, 100 U/ml IL-2, 5 ng/ml IL-7, and 5 ng/ml IL-15." (PMID 34099861, 2021). "Overall, these results demonstrate the therapeutic potential of IL-2 and anti-TGF-β to meaningfully accelerate NK cell reconstitution and function without treatment-related toxicities resulting in greater protection from cancer relapse." (PMID 33138229, 2020). "Using a nine color flow cytometry panel, we similarly assessed whether the expression of IL-2/12 receptor subunits [CD25 (α), CD122 (β), CD132 (γ), and CD212 (β1)] could be detected in 13 healthy donors and 11 cancer patients." (PMID 32508837, 2020). "The dependence of TERT expression on all three signaling pathways with IL-2 and with IL-15 in CD8 T cells, suggests that any therapies that inhibit MEK/ERK pathways used in cancer patients are likely to affect proliferation of CD8 T cells to a greater extent than NK cells or NK-like cells." (PMID 33537030, 2020). "For example, the decreased expression of CD3ζ chains in cancer patients is not reversed by IL-2 administration." (PMID 32316275, 2020). "According to our results, when the OVCAR3 were not treated, the supernatant of the untreated cancer cells presented a significant presence of IL2." (PMID 32326210, 2020).
cancer (continued). "Importantly, both MS4A1 and TIL-B levels are consistently prognostic across five cancer types, namely HNSCC, LUAD, CESC, LGG, and KIRP, with distinct Be2 and BK signatures (especially for IL2, IL6, and PD-L2 expressions)." (PMID 32398659, 2020). "TILs kill cancer cells by releasing cytokines, such as IFN-γ, IL-2, and TNF-α." (PMID 32964058, 2020). "This implies that the replication of OAd.TNFa-IL2 is cancer-cell specific as designed and does not harm normal cells such as DCs." (PMID 32225009, 2020). "Like phenotyping, intracellular staining of cytokines upon co-culture with cancer cells did not prompt any explanations about the enhanced cytotoxicity in IL-2/IL-15-expanded cells." (PMID 32983105, 2020). "The E.G7 cancer cells were able to suppress dendritic cell activation of OVA-specific CD4+ T cell IL-2 production relative to T cell activation in the absence of E.G7." (PMID 31602007, 2019). "Beside the benefits of TAB004 as an early monitoring approach to detect cancers earlier and monitor their progression, these data indicate that TAB004 may also have clear therapeutic benefits when combined with IL-2 to stimulate a targeted immune response." (PMID 31114758, 2019). "From mouse studies, it is thought that TCM may be more protective and effective against cancer compared to TEM, in part due to their high levels of IL-2 production and capacity for proliferation." (PMID 31379821, 2019). "The activation action of the collected fractions on Natural Killer cells was quantified against three different cancer cell lines in the presence or absence of human recombinant IL2 using three different activation and co-culture conditions." (PMID 31457012, 2019). "Because cytokine secretion by CAR-T cells targeting cancer cells indicates the activation and specific cytotoxicity of T cells, we analyzed the levels of the classic cytokines, TNF-α, IL-10, INF-γ, and IL-2, to assess the cytokine profile when CAR-T cells were incubated with U-251MG cells." (PMID 31288857, 2019). "Seminal studies have shed light on T-cell exhaustion in human cancers, where CD8 T cells lose proliferative capacity, the ability to produce tumor necrosis factor (TNFα), interleukin-2, and interferon-γ (IFNγ), and upregulation of inhibitory checkpoint receptors, such as PD-1 and CTLA-49–11." (PMID 31804466, 2019). "The activated markers of MU pre-treated NK cells in co-culture models with cancer cells in the presence or absence of Il2 were quantified using qRT-PCR to detect the expression levels of INFγ, NKG2D and KIR2D genes." (PMID 31457012, 2019). "The anticancer effect of Mu1 activated NK cells (activated for 3 days and co-incubated with cancer cells for 5 days at a 1:3 ratio with either MCF7 or A549 were evaluated in with or without IL-2." (PMID 31457012, 2019). "Accordingly, IL-2 secretion increased by KLDS1.0318 may stimulate T-cell proliferation and IFN-γ production, which in turn improves the immune response against cancer and pathogen-infected cells." (PMID 30026678, 2018). "In the last two decades, the potential of IL-2 to expand T cells without affecting its activity has led to identification of its potential as an immunotherapeutic agent against cancer." (PMID 29854806, 2018). "In the 1980s, Rosenberg and colleagues were first to show the potential of immunotherapy in treating malignancies by employing lymphokine-activated killer cells (LAK) produced by taking blood from the patients and treating their lymphocytes with interleukin 2 (IL-2)." (PMID 30613448, 2018). "Pro-inflammatory cytokines present in the media, including IL-2 and CD3/CD28 beads, may have contributed to untransduced T cell activation, leading to granzyme and perforin release and detectable cancer cell death." (PMID 29255242, 2017).